CYP1A1 (cytochrome P450 family 1 subfamily A member 1)
Diseases named in the same sentence as CYP1A1 in open-access papers (continued):
Sharing a sentence is not in itself a finding about the gene and the disease.
psoriasis (16 papers, 2018 to 2025). An autoimmune condition characterized by red, well-delineated plaques with silvery scales that are usually on the extensor surfaces and scalp. "Several SNPs in the CYP1A1 gene have been linked to increased enzymatic activity, and their contribution to the difference detected in patients with psoriasis remains to be investigated." (PMID 33385398, 2021). "Endogenous AhR ligands, such as FICZ, improve skin inflammation in psoriasis by inducing CYP1A1 expression and reducing the transcription/expression of psoriasis-related genes." (PMID 41425939, 2025). "A previous study investigating the AhR-CYP signaling pathway in patients with exacerbated psoriasis reported a significant increase in serum CYP1A1 expression." (PMID 40864793, 2025). "CYP1A1 activity remained significantly increased in patients with psoriasis compared with that in healthy controls when the analysis was restricted to nonsmoker individuals." (PMID 33385398, 2021). "This can be of importance in the presence of increased CYP1A1 activity as we have detected in patients with psoriasis versus that in controls." (PMID 33385398, 2021). "We detected significantly increased CYP1A1 enzymatic activity in patients with psoriasis compared with that in healthy controls." (PMID 33385398, 2021). "Simultaneously, epidermal AhRR and CYP1A1 mRNA expression in psoriasis skin tissue was significantly increased compared to healthy skin tissue." (PMID 34884515, 2021). "Nevertheless, CYP1A1 activity remained significantly increased in Th17 cells of patients with psoriasis compared with the activity in Th17 cells of healthy controls when our analysis was restricted to nonsmoker individuals." (PMID 33385398, 2021). "We found that cells of patients with psoriasis had significantly higher CYP1A1 activity than those of healthy controls." (PMID 33385398, 2021). "In human psoriasis skin lesions, the level of AhR and CYP1A1 proteins and transcripts was upregulated, while LC3 was downregulated at both mRNA and protein level, compared to controls." (PMID 32235789, 2020). "In human psoriasis lesion skin, the expression level of CYP1A1 and AhR was increased and LC3 was decreased compared to controls." (PMID 32235789, 2020). "AhR and CYP1A1 expression was significantly higher in TCDD-treated-psoriasis lesion skin tissues compared to TCDD-treated controls." (PMID 32235789, 2020). "In contrast, serum levels of both AHR and CYP1A1 are elevated in patients with psoriasis compared to normal controls." (PMID 31683543, 2019). "Immunohistological and real time PCR studies have demonstrated that the expression of AHR and ARNT is upregulated in the lesional skin of psoriasis, whereas CYP1A1 expression was significantly decreased compared to normal controls." (PMID 31683543, 2019). "Furthermore, CYP1A1 activity is significantly elevated in the blood cells of patients with psoriasis compared to healthy controls, suggesting its role in modulating psoriasis-related inflammation." (PMID 40864793, 2025). "This analysis revealed a significant interaction between CYP1B1 and CYP1A1, suggesting that these proteins may represent key molecular targets through which Inulae Flos exerts its potential therapeutic effects in psoriasis." (PMID 40864793, 2025). "Furthermore, integration with psoriasis-related gene data revealed five overlapping genes, with CYP1A1 and CYP1B1 emerging as core targets." (PMID 40864793, 2025). "Further investigation into whether IDG NE mitigates IMQ-induced psoriasis-like skin inflammation through the activation of AhR signaling was conducted via Western blotting analysis to detect CYP1A1 protein expression in skin lesion tissues." (PMID 39465158, 2024).
psoriasis (continued). "Dysregulation of AHR by either genetic deficiency or by excess activity of the downstream negative regulator Cyp1a1 causes skin pathology, and patients suffering from psoriasis display reduced activity of the AHR pathway and increased enzymatic activity of Cyp1a1 compared with healthy donors." (PMID 39242971, 2024). "In this study, we hypothesize that CYP1A1 feedback regulates skin inflammation and that upregulation of its enzymatic activity may occur in patients with psoriasis, disrupting the anti-inflammatory effect mediated by physiological AHR signaling." (PMID 33385398, 2021). "Nevertheless, because we are not dissecting the pathogenic role of Th17 cells in psoriasis but rather using them as a robust model system to measure CYP1A1 enzymatic activity, their usage is not in contrast with the beneficial role of the AHR pathway." (PMID 33385398, 2021). "Next, we investigated CYP1A1 activity in healthy controls and in patients with psoriasis." (PMID 33385398, 2021). "Therefore, when comparing patients with psoriasis (n = 15) and healthy controls (n = 20), we measured the amount of IL-17A in the supernatant of each culture and subsequently used it to normalize CYP1A1 activity." (PMID 33385398, 2021). "Although imiquimod-induced skin inflammation is popular as a psoriasis model, attention should be paid because imiquimod is degraded by CYP1A1 so the efficacy of AHR agonists may partly rely on this effect in the imiquimod model." (PMID 31683543, 2019). "Moreover, increased CYP1A1 activity in Th17 cells could potentially contribute to skin inflammation in patients with psoriasis by limiting the activation of AHR signaling in KCs." (PMID 33385398, 2021). "The effect of increased CYP1A1 metabolic activity and potential reduction of AHR ligands was much more prominent in R26Cyp1a1 mice undergoing psoriasis-like inflammation." (PMID 33385398, 2021). "The level of CYP1A1, AhR, and LC3 expression was determined by immunohistochemistry, and qPCR in human healthy skin (control) and human psoriasis lesion skin." (PMID 32235789, 2020). "Interestingly, we found excessive CYP1A1 enzymatic activity in in vitro-expanded Th17 cells from psoriasis patients, suggesting a possible dysregulation of the AHR/CYP1A1 axis in psoriasis leading to reduced AHR activation." (PMID 40004095, 2025). "Thus, the expression of CYP1A1 is significantly decreased in lesional skin, suggesting that activation of the AHR pathway is impaired in psoriasis." (PMID 33385398, 2021). "First, we evaluated the expression of CYP1A1 in the skin comparing normal (n = 42), lesional psoriasis (n = 22), and nonlesional psoriasis (n = 15) biopsy samples." (PMID 33385398, 2021). "For example, the reported dysbiosis of the psoriasis skin microbiome, with a reduction in certain commensals such as Lactobacilli, may be responsible for reduced availability of AHR ligands, resulting in reduced AHR activation and CYP1A1 expression." (PMID 40004095, 2025). "Abnormal expressions of CYP1A1 and CYP2E1, members of the cytochrome P450 (CYP450) family, are closely related to the occurrence and development of psoriasis, which may affect the normal metabolism of ginkgolic acid, thereby leading to a marked elevation in plasma expression levels." (PMID 35463691, 2022). "Importantly, patients with psoriasis displayed reduced activation of the AHR pathway and increased CYP1A1 enzymatic activity compared with healthy donors, suggesting that dysregulation of the AHR/CYP1A1 axis may play a role in inflammatory skin disease." (PMID 33385398, 2021). "Interestingly, in agreement with our data in mice, patients with psoriasis displayed increased CYP1A1 enzymatic activity compared with healthy donors, suggesting that dysregulation of the AHR/CYP1A1 axis may play a role in inflammatory skin disease." (PMID 33385398, 2021).
esophageal cancer (15 papers, 2001 to 2024). A primary or metastatic malignant neoplasm involving the esophagus. "Although many epidemiologic studies have investigated the CYP1A1 MspI gene polymorphisms and their associations with esophageal cancer (EC), definite conclusions cannot be drawn." (PMID 25886559, 2015). "The results of this study found that those cases with the CYP1A1 Val/Val genotype had a 2.34 times higher risk (95% CI=1.13–4.85) of developing oesophageal cancer than those with the Ile/Ile genotype." (PMID 12189551, 2002). "One other Breton team has examined the genetic polymorphism of two P450 cytochromes (CYP2EI and CYP1A1) among alcoholic patients with diverse complications (including cirrhosis and oesophageal cancer) and control subjects, but was unable to demonstrate a significant difference." (PMID 20069042, 2009). "The majority of the studies including the present study suggest that esophageal cancer can be associated with mutations of CYP1A1, CYPA1A MspI T/C, CYP1A1 A2455G, CYP1A1T3801C A2455G, and a threefold increased risk for esophageal malignancy observed in patients with CYP2C19PM phenotype variant." (PMID 36035062, 2022). "In summary, this study found CYP1A1 exon 7 (but not MspI) polymorphism to be a factor in elevated oesophageal cancer risk." (PMID 12189551, 2002). "In contrast, we found no significant polymorphic effect of CYP1A1 MspI on oesophageal cancer." (PMID 12189551, 2002).
gastric cancer (15 papers, 2007 to 2024). A primary or metastatic malignant neoplasm involving the stomach. "The Kaplan-Meier analysis showed that upregulation of CYP1A1 gene is associated with worse survival in gastric cancer patients." (PMID 38274743, 2023). "According to the Kaplan-Meier Plotter survival analysis, a higher level expression of CYP1A1 is associated with poor prognosis in gastric cancer patients, with a hazard ration of 1.86 and median survival period of 20.4 months as opposed to 56.9 months in low expression cohort." (PMID 38274743, 2023). "Moreover, CYP1A1 polymorphisms in smokers increase susceptibility to stomach cancer." (PMID 32097409, 2020). "Furthermore, the stomach expresses cytochrome P450 isoforms including CYP1A1 and significant associations between CYP1A1 polymorphisms and gastric cancer risk have been reported in humans, suggesting that the altered function of AhR-downstream molecule induces the stomach abnormality." (PMID 31226941, 2019). "The role of the upregulated CYP1A1 gene in gastric cancer survival was assessed using the Kaplan-Meier method." (PMID 38274743, 2023). "The results showed that taxifolin significantly inhibited the survival, proliferation, migration, invasion and tumor growth of gastric cancer through the aryl hydrocarbon receptor (AhR)/cytochrome P450 1A1 (CYP1A1) signaling pathway." (PMID 37261284, 2023). "This is further supported by the survival analysis of CYP1A1 in gastric cancer patients." (PMID 38274743, 2023). "In addition, we noted that some genes (such as CYP1A1, STC2, ASNS, etc.)listed in association with the tumour cell survival, cell proliferation, and cell death also affect the survival of gastric cancer patients under adjuvant chemotherapy." (PMID 30380689, 2018). "The activation of AHR and CYP1A1 and CYP1B1 related pathways promotes the proliferation and migration of gastric cancer cells." (PMID 34784845, 2021). "Faint constitutive expression of CYP1A1 and CYP2W1 was detected in cytoplasm and nuclei of MNK‐45 gastric cancer cells." (PMID 31876059, 2020). "A decline in AhR protein levels and an increase in cytochrome P450 1A1 (CYP1A1) expression in a dose- and time-dependent manner observed after treatment with DIM demonstrate the correlation between AhR and gastric cancer." (PMID 27447608, 2016). "In contrast, in all other gastric cancer cell lines within this panel, CYP1A1 induction was not evident (results not shown)." (PMID 31876059, 2020).
liver cancer (15 papers, 2020 to 2025). An epithelial or non-epithelial malignant neoplasm that arises from the liver. "The mechanism of CDCA treatment in liver cancer is associated with the upregulation of CYP1A1 induced by the activation of MEK1/2." (PMID 38760843, 2024). "In liver cancer cells, over-expression of CYP1A1 induced by plant natural products has been associated with Aryl-hydrocarbon Receptor transformation." (PMID 32730293, 2020). "Elevated expression of Cyp1a1 has been proposed as a potential biomarker for liver cancer progression and metastasis." (PMID 40864826, 2025). "Modulation of Cyp1a1 expression and activity has thus been suggested as a potential strategy to improve treatment outcomes in liver cancer." (PMID 40864826, 2025). "In conclusion, our study suggests that the CCL5/CCR5/CYP1A1 pathway is activated during combination therapy to mediate metabolic reprogramming of liver cancer cells to resist lenvatinib." (PMID 39183447, 2024). "Collectively, this study is aimed at investigating the specific effects and mechanism of ZNF165/AhR/CYP1A1 on liver cancer cell aggressiveness." (PMID 35692498, 2022). "The level of AHR is reportedly significantly elevated in various forms of cancer, including breast, ovarian, and liver cancers, and the AHR target genes of CYP1A1 and CYP1A2 are also linked to prognosis." (PMID 34373448, 2021). "Despite BAI being an AHR agonist and upregulating CYP1A1 expression in human HepG2 liver cancer cells, it paradoxically reduces the AHR-mediated CYP1A1 expression induced by 7,12-dimethylbenz[a]anthracene (DMBA)." (PMID 32526964, 2020). "During its enzymatic activity, Cyp1a1 generates reactive oxygen species (ROS), leading to oxidative stress, DNA damage, and chronic inflammation—factors known to contribute to the development of liver cancer." (PMID 40864826, 2025). "In order to investigate whether ZNF165 regulates the cell phenotypes by CYP1A1, we knocked down CYP1A1 and evaluated the proliferation and migration of the liver cancer cells." (PMID 35692498, 2022). "In addition, downregulation of CYP1A1 could impair its ability to form clones in liver cancer cells." (PMID 35692498, 2022). "In this study, we first found that curcumin induced changes in the expression of CYP1A1, HMGCS2, HMOX1, LCN2, and MTTP, which are enriched in metal ion homeostasis, in all three liver cancer cell lines." (PMID 36838613, 2023). "Subsequently, we discovered the CCL5/CCR5/CYP1A1 pathway through RNA sequencing (RNA‐seq) on CCL5‐stimulated Huh7 cells and verified through a series of experiments that this pathway can mediate the resistance of liver cancer cells to lenvatinib." (PMID 39183447, 2024). "Importantly, in this study, EO induced cell apoptosis in HepG2 liver cancer cells through the activation of mRNA of CASPASE-3 and CYP-1A1." (PMID 35009072, 2021). "Although BAI was shown to induce CYP1A1 expression in HepG2 liver cancer cells, it did not exhibit CYP1A1 upregulation in NHEKs but it induced only minimally in HaCaT cells, 10 times lower than that of BaP." (PMID 32526964, 2020). "Furthermore, the downregulation of ZNF165 could significantly decrease the expression of AhR, CYP1A1, and CYP1B1 in liver cancer cells." (PMID 35692498, 2022). "In liver cancer cells, AHR was found to be critical in base excision repair where methylated cytosine was replaced by nonmethylated cytosine in the CYP1A1 promoter, leading to increased CYP1A1 RNA expression." (PMID 40765830, 2025).
colon carcinoma (14 papers, 2006 to 2025). "Colonic cancer cells were found to express higher levels of CYP1A1/1B1/2E1 and GST isoforms in comparison to a healthy colonic epithelium, suggesting this signature to be a useful marker for the prognosis of cancer progression." (PMID 35811943, 2022). "Colon tumors revealed a higher correlation coefficient between T/N expression ratio of CYP1A1 mRNA and T/N expression ratio of CYP1 activity compared to bladder tumors (R = 0.74)." (PMID 24358191, 2013). "CYP1B1 mRNA was overexpressed in 65% and 60% of bladder and colon tumors respectively, whereas CYP1A1 was overexpressed in 65% and 80% of bladder and colon tumors." (PMID 24358191, 2013). "This is one of the few studies that substantiate the implication of CYP1B1 and CYP1A1 to a lesser extent, in cancer therapy due to their differential enzyme activity overexpression in bladder, and colon tumors." (PMID 24358191, 2013). "It is reported that the expression of CYP1A1 mRNA was shown after 6 hours and sustained for up to 72 hours in human colon carcinoma cells treated with TCDD." (PMID 16704738, 2006). "These in silico findings, together with great effects on SW-480 and HT-29 colon cancer cells, provide a foundation for further experimental validation and characterization of isorhamnetin’s interactions with target proteins, including CYP1A1, CYP1B1, P-gp, MRP1, and MRP5." (PMID 40649986, 2025). "Colon tumor tissues presented a higher frequency of CYP1A1 overexpression." (PMID 24358191, 2013). "The HDAC inhibitors butyrate, panobinostat and vorinostat enhanced TCDD-mediated induction of Cyp1a1/CYP1A1 in the murine YAMC and human Caco-2 colon carcinoma cell lines, respectively." (PMID 37696456, 2023). "Treating additional colon cancer cells with Kyn also promoted AHR nuclear translocation and induced the expression of the canonical of AHR target gene CYP1A1." (PMID 31416966, 2019). "Initial studies with butyrate demonstrated that this compound significantly increased expression of Ah-responsive genes such as Cyp1a1/CYP1A1 in YAMC mouse colonocytes and Caco-2 human colon cancer cell lines." (PMID 28860561, 2017). "Over-expression of CYP1A1 and CYP1B1 in human colon tumors implies a pro-carcinogenic role for AhR target genes." (PMID 26264025, 2015). "Mean mRNA levels of CYP1B1 and CYP1A1 along with mean CYP1 activity were higher in bladder and colon tumors compared to normal tissues (p<0.05)." (PMID 24358191, 2013). "Notably, these results also differ from our previous study, where 5-FU increased the mRNA expression of CYP1A1 and CYP1B1 in the same colon cancer cell lines." (PMID 40649986, 2025). "Although many other CYP isoforms contribute to these processes and their analysis could provide additional valuable insights, we focused on CYP1A1 and CYP1B1 because these isoforms are frequently overexpressed in colon cancer cells." (PMID 40649986, 2025). "Increased levels of CYP1A1 mRNA by Avitriptan were observed in human colon carcinoma cells LS180 but not in primary cultures of human hepatocytes." (PMID 32316498, 2020). "As a next step, our studies will explore the underlying mechanisms of how WD modulates B(a)P biotransformation enzymes (CYP1A1, CYP1B1, glucuronosyltransferase, sulfotransferase, and glutathione-S-transferases) and increases the number of colon tumors compared to RD." (PMID 26959117, 2016). "When mean expression levels of CYP1A1 and CYP1B1 mRNA were compared in the entire panel of bladder or colon tissues the analysis indicated that expression levels of CYP1A1 and CYP1B1 mRNA were higher in bladder and colon tumors compared to normal tissues (p < 0.05)." (PMID 24358191, 2013).